LEP (leptin)
Diseases named in the same sentence as LEP in open-access papers (continued):
Sharing a sentence is not in itself a finding about the gene and the disease.
Obesity (continued). "Therefore, obese women could be providing inadequate milk leptin levels to their infants, and this is of relevance since leptin has been associated with obesity prevention at the early stages of life through milk supply." (PMID 36986066, 2023). "Future studies should focus on whether leptin alone or the adiponectin/leptin ratio is diagnostic or useful for treatment or survival indications for pancreatic adenocarcinoma patients, and especially ones who also have the co-morbid condition of obesity." (PMID 37181043, 2023). "Furthermore, chronic low-grade inflammation and increased levels of circulating pro-inflammatory cytokines associated with obesity, such as leptin, tumor necrosis factor a, and interleukin 6, may impair immune response and affect the lung parenchyma." (PMID 37373748, 2023). "Studies show that several biomarkers are potential mediators in the pathogenesis of obesity and these include hormonal markers such as adipokines and cytokines, which are adipose tissue hormones and genetic markers such as those associated with leptin signaling." (PMID 37239728, 2023). "However, obesity causes systemic inflammation, which leads to leptin resistance." (PMID 37363537, 2023). "Thus, leptin resistance may play a crucial role in age-associated weight gain and obesity, although underlying mechanisms are poorly understood." (PMID 38068822, 2023). "Additionally, leptin-linked pathways, which regulate the equilibrium between energy and appetite, are likely to be responsible for the connection between teeth brushing and obesity." (PMID 36900046, 2023). "However, since obesity is now considered a risk factor for many cancers, the p73γ-Leptin pathway may provide a physiological link between cancer and obesity." (PMID 37650871, 2023). "However, the causative relations between leptin resistance and age-related obesity are disputable." (PMID 38068822, 2023). "Specifically, obesity is a metabolic pathogenic state that courses with systemic chronic low-grade inflammation and high circulating levels of inflammation-related markers (e.g., leptin, IL-6, TNF), which may affect tumor growth." (PMID 37819510, 2023). "Furthermore, Th1 polarization correlated with leptin, an adipokine associated with obesity-mediated inflammation, and IL-6, a cytokine downstream in the leptin inflammatory pathway, suggesting that obesity was driving the Th1 systemic inflammation in obese children with asthma." (PMID 38292857, 2023). "A major underlying factor driving the pathogenesis in obesity and metabolic syndrome is the presence of a chronic low-grade inflammation, which is characterized by increased circulating IL-6 and other cytokines, as well as altered levels of adipokines, such as leptin and adiponectin." (PMID 37841878, 2023). "Visceral adipose tissue is also resistant to insulin and leptin and is the site of altered secretion of molecules and hormones such as adiponectin, leptin, resistin, tumor necrosis factor and interleukin-6, which exacerbate cardiovascular disease associated with obesity." (PMID 37081416, 2023). "Indeed, we found that umami (both glutamate and IMP) could generate uric acid and cause hepatic ATP depletion, leptin resistance and obesity and metabolic syndrome similar to fructose." (PMID 37482773, 2023). "Although at first sight this effect might be partly explained by the association of leptin with obesity, the leptin receptor is widely expressed in many tissues, including the lung, and thus a direct effect of leptin on pulmonary structures cannot be discarded." (PMID 38086735, 2023). "Obesity can be considered a metabolic complication, which, in addition to the high percentage of fat, is associated with a generalized inflammatory state, which can be observed by the oscillation of some pro-inflammatory cytokines, with leptin being one of the main ones." (PMID 38015889, 2023).
Obesity (continued). "Therefore, the excess nutrients intake characterizing obesity associates with higher levels of inflammatory hormones (i.e. leptin) secreted by adipose tissue, leading to a metabolic reprogramming of immune cells, in particular macrophages, towards a pro-inflammatory phenotype." (PMID 37358728, 2023). "Moreover, since obesity is often associated with leptin resistance, and obesity itself increases the risk of BC, the data presented in this report suggest that leptin resistance could be one of the links between obesity and BC risk." (PMID 37892180, 2023). "The influence of obesity on fertility may be associated with an increased leptin concentration, hypoadiponectinemia, a high concentration of triglycerides and free fatty acids in ovarian follicular fluid, and also the presence of oxidative stress and inflammatory mediators." (PMID 37371662, 2023). "Additionally, obesity can cause leptin resistance and impact Leydig cell responsiveness." (PMID 38089610, 2023). "Moreover, they noted that after 24 weeks of nourishing a high-fat/high-sucrose diet for wild-type mice, leptin deficiency mice (ob/ob) and Zucker diabetic fatty mice (fa/fa) resulted in obesity phenotype, down-regulation of SFRP5 expression, and overexpression of WNT5A." (PMID 37542207, 2023). "According to the role of obesity in metabolic syndrome, the high risk of moderate/severe ED may be due to pathophysiologic processes, including oxidative stress, inflammation, and insulin and leptin resistance." (PMID 37065736, 2023). "Additionally, leptin resistance indicates an increased susceptibility to diet-induced obesity." (PMID 36835164, 2023). "Furthermore, adipose tissue in patients with obesity is associated with upregulation of immune checkpoints on T-cells that is partially mediated via immunomodulatory effects of leptin and has been paradoxically associated with improved responses to immunotherapy in several cancers." (PMID 37173907, 2023). "MicroRNAs may be implicated in obesity and in modifications in leptin signaling activation." (PMID 36674935, 2023). "Obesity has been linked to a higher incidence of miscarriage, This may be due to the high levels of leptin found in obese individuals, which can lead to insulin resistance through altered fatty acid metabolism in skeletal muscle, as well as a pro-inflammatory shift in the immune system." (PMID 38433972, 2023). "Indeed, leptin is associated with cytokine storm during COVID-19 infection in obesity, and it may modulate the gene expression in cardiomyocytes, which may cause myocardial ischemia." (PMID 37217748, 2023). "Leptin and its receptors were overexpressed in patients with CP, and high preoperative plasma leptin was independently associated with significant weight gain and new-onset obesity, indicating the potential role of leptin resistance in the pathogenesis of obesity in CP." (PMID 37509115, 2023). "However, leptin resistance is commonly associated with obesity." (PMID 37761175, 2023). "In this review, we discuss different leptin resistance mechanisms that could be implicated in increasing the risk of developing AD, as leptin resistance is frequently associated with obesity, which is a chronic low-grade inflammatory state, and obesity is considered a risk factor for AD." (PMID 35563589, 2022). "Finally, pro-obesity gut microbiota can significantly contribute to fat accumulation and increase susceptibility to obesity by reducing sensitivity to hormones, such as leptin, or inhibiting the expression of the obesity-suppressing neuropeptides, such as proglucagon." (PMID 35204214, 2022). "In obesity, despite increased leptin concentrations, the efficacy of the anorexic effect of this adipokine is decreased and leptin resistance is developed due to a defect in intracellular signaling associated with the leptin receptor or decreases in leptin transport across the blood–brain barrier." (PMID 35745249, 2022).
Obesity (continued). "The excess of leptin associated with obesity and the stimulation of T cells by adipocytes might result in an overactivation of T cells and alterations in T cell populations in the visceral adipose tissue, with the putative consequence of a suppressed systemic antiviral response." (PMID 36246898, 2022). "Moreover, obesity associated with high leptin levels can lead to chemotherapy resistance." (PMID 35563103, 2022). "Furthermore, leptin and insulin influence risk of pre-eclampsia independently of obesity." (PMID 35104295, 2022). "Therefore, obesity in humans may represent a state of leptin resistance, which can cause IR through a variety of pathways." (PMID 35498804, 2022). "IF seems to modulate inflammatory pathways in the brain, which may also be correlated with the brain-microbiota axis, improving hypothalamic signaling of leptin and insulin, and inducing the autophagic pathway in hypothalamic neurons, contributing to weight loss in obesity." (PMID 35445066, 2022). "Additionally, the reduced level of SM in Hh-KO mice, which were more pronounced in females, are in line with findings in the obese ob/ob mouse model, which is characterized by massive obesity caused by a mutation in the leptin gene which is the main regulator for food intake." (PMID 35626717, 2022). "Furthermore, the work showed that on the one hand, leptin and insulin influence the risk of PE independently of obesity, but on the other hand, leptin, fasting insulin, and insulin resistance each mediated between 20% and 50% of the total genetically predicted association of obesity with PE." (PMID 36556383, 2022). "Obesity is associated with chronic low-level inflammation and hypoxia that can lead to genomic instability, elevated production of growth factors and adipokines such as estrogen and leptin, altered microbiota, and pro-inflammatory signaling combined with elevated immunosuppression." (PMID 35870055, 2022). "Characterization of tumor-derived EV protein cargo in an obesity-associated milieu, such as in the presence of elevated leptin levels, might allow identifying unique features and specific biological processes to be targeted in the clinical management of breast cancer." (PMID 36361728, 2022). "Therefore, hyperglycemic microenvironments rich in insulin, TCR ligands, and leptin, such as the ones associated with obesity and T2D, tend to result in inflammatory and metabolic diseases that impact the individual risk of developing other chronic co-morbidities." (PMID 36033972, 2022). "Thus, our results allow us to infer that the synergistic effect of vitamin D deficiency and obesity could explain the significant increase in plasma leptin levels observed in the HFDV group." (PMID 36466412, 2022). "investigated, whether Metreleptin administration for 12 months has an impact on the global NASH score in adults with obesity and with relative leptin deficiency (individual leptin level <25th percentile for leptin levels related to age and BMI of a reference group)." (PMID 35677722, 2022). "Therefore, we will analyse the information on inflammation-induced leptin resistance that occurs during obesity as a pathological mechanism that may underlie neurodegenerative diseases such as AD and other dementias." (PMID 35563589, 2022). "Therefore, an increased abundance of Lactobacillus and Bifidobacterium and a decreased abundance of Bacteroides taxa in obese individuals may result in leptin resistance that fuels obesity, a well-known risk factor of CAD." (PMID 36557203, 2022). "Furthermore, severe obesity was found in congenitally leptin-deficient humans of Pakistani origin caused by a homozygous frameshift mutation consisting of a single guanine deletion in codon 133 (Δ133G or g.13374delG) of the LEP gene, affecting the protein p.Gly133Valfs*15." (PMID 35563103, 2022).
Obesity (continued). "Moreover, gut microbiota might be associated with leptin resistance, which is in general developed in obesity, throughout interfering hypothalamic and brainstem neural processes, involved in feeding and energy balance control." (PMID 36225863, 2022). "Moreover, increased production of visfatin and leptin serum levels may lead to the increased release of Th1 cytokines and result in obesity and its association with diabetes." (PMID 35468098, 2022). "Leptin resistance is defined by a reduced sensitivity or failure in response of the brain to leptin, showing a decrease in the ability of leptin to suppress appetite or enhance energy expenditure, thus causing increased food intake and finally leading to overweight and obesity." (PMID 36329131, 2022). "Although leptin showed excellent results in reversing many metabolic and cognitive dysfunctions in rodent models, and in leptin deficient humans, clinical trials with recombinant leptin in subjects with common obesity consistently reported disappointing outcomes." (PMID 35527735, 2022). "Interestingly, pregnant women with obesity with high cord blood leptin may have an increased risk of asthma." (PMID 36613991, 2022). "In fact, obesity in patients with narcolepsy may be caused by a variety of causes, such as: less physical activity, binge eating behavior, low metabolic rate, reduced sympathetic tones, growth hormone deficiency, and reduced plasma leptin level." (PMID 36422261, 2022). "Obesity is also considered one of the OA risk factors due to it increasing the mechanical stress on the knee joint and adipocytes under obesity and release adipokines, such as leptin and resistin with elevated levels of proinflammatory cytokines and matrix metalloproteinases." (PMID 35509713, 2022). "To address the molecular processes going on with the accumulation of AT during obesity development and progression in children in more detail, we next searched for gene expression associations with the functional AT parameters adipocyte size, leptin, adiponectin, and/or macrophage infiltration." (PMID 35457174, 2022). "We tested this hypothesis by examining the antiobesity effect of SFN on two established genetic models of obesity, namely, the leptin-deficient Lepob/ob and the leptin receptor mutant Leprdb/db mice, both of which develop early-onset hyperphagic obesity due to deficient leptin signaling." (PMID 35323110, 2022). "In addition, obesity can cause an increase in leptin, which can then increase SNS activity." (PMID 35743756, 2022). "As dysregulation of leptin may result in an abnormality in satiety and thereby associated to obesity, the investigation of leptin-cortisol sparse dynamics may offer a better diagnostic methodology to improve better treatments plans for individuals with obesity." (PMID 35480480, 2022). "Therefore, several studies point toward leptin resistance instead of loss of leptin during obesity." (PMID 35958993, 2022). "Moreover, various polymorphisms in the LEP gene are linked to extreme obesity, such as D7S514, D7S680, D7S530, D7S504, and D7S1875, while the most frequently studied LEP SNPs are rs7799039, rs2167270, rs4731426, rs2071045, and rs17151919 as determinants in obesity." (PMID 35563103, 2022). "Differences in sensitivity to metabolic hormones and adipokines, such as leptin and insulin, may underlie some of the sex differences in the prevalence of type 2 diabetes and obesity, and interestingly, these hormones and adipokines are often altered by the nutritional environment of early life." (PMID 36439251, 2022). "In addition, several inflammatory cytokines associated with obesity, such as adiponectin and leptin, may aggravate the inflammatory process induced by noise exposure." (PMID 36312318, 2022).
Obesity (continued). "Considering that obesity, which is a hyperleptinemia condition, represents an important risk factor for heart failure, more studies are necessary to investigate the possible association between increased leptin sensitivity and the occurrence of arhythmic events, especially in aged individuals." (PMID 35742928, 2022). "Furthermore, leptin resistance may represent an underlying mechanism linking obesity with depression with atypical features, like hyperphagia." (PMID 35758834, 2022). "Moreover, LEP polymorphisms described so far have shown variations related to the obesity form or grade, which may be the result of other influencing factors such as clinical features." (PMID 35563103, 2022). "Obesity causes hypertrophy and proliferation in adipocytes, leading to a rapid increase in adipose tissue, and when angiogenesis cannot match the expanded AT, local hypoxia in AT causes an increase in pro-inflammatory leptin and a decrease in anti-inflammatory adiponectin." (PMID 36568121, 2022). "Leptin, a hormone produced by adipose tissue, plays an important role in the control of energy homeostasis, the excess and resistance of which are associated with obesity, leading to failures in the signaling mechanisms associated with decreased nutrition and body weight control." (PMID 35237168, 2022). "Various conditions predispose to fatty liver including obesity and diabetes, while countervailing physiologic forces may reduce liver fat, including weight loss from energy restriction, exercise, and hormonal changes such as increased leptin." (PMID 36162520, 2022). "Therefore, considering the success in obesity management based on congenital or acquired LEP mutations, progress toward elucidating the mechanisms linking obesity and CRC may be a potential direction for compiling new strategies and tools in medicine." (PMID 35563103, 2022). "Since its discovery in 1994, leptin replacement therapy has been extensively investigated in rodent models as well as in children and adults, where parenteral leptin replacement therapy has been approved for the treatment of congenital leptin deficiency, diabetes, and obesity." (PMID 36558383, 2022). "Furthermore, leptin and IL-6 were associated with individuals with obesity and PD." (PMID 36547041, 2022). "Therefore, treating triglyceride levels in the blood could decrease central (and peripheral) resistance to leptin and reduce obesity and the cognitive problems associated with it." (PMID 35563589, 2022). "Additionally, we observed a positive association between pre-pregnancy obesity and leptin." (PMID 35406128, 2022). "Experimental blockage of the neonatal leptin surge affects gene expression of growth factors, glial proteins, and neuropeptides involved in the control of metabolism and reproduction in peripubertal male and female rats and is associated with increased susceptibility to develop diet-induced obesity." (PMID 36619540, 2022). "It has been reported that leptin, resistin, and adiponectin, which are involved in mediating obesity, have been linked to increased oxidative stress and inflammation, which may cause a global health risk leading to hyperglycemia, cancer, diabetes, and other diseases affecting vital organs." (PMID 36500974, 2022). "Thus, it is possible that sustained PLAC8 overexpression could play a central role in the pathophysiological association between obesity and preeclampsia, maintaining the expression of leptin." (PMID 35252239, 2022). "In the past few years, new mutations in the LEP gene related to obesity and its associated disorders have been identified, which may be important for enabling progress toward understanding the physiopathology of obesity and its specific management." (PMID 35563103, 2022).